FGF21 (fibroblast growth factor 21)
Diseases named in the same sentence as FGF21 in open-access papers (continued):
Sharing a sentence is not in itself a finding about the gene and the disease.
Hyperglycemia (continued). "In summary, the present findings suggest that expression of the hepatic htr2b is increased in young diabetic db/db mice and KKAy mice, and pharmacologic inhibition of htr2b ameliorates the hyperglycemia and altered expression of hepatic FGF21, Sdf2l1 and htr2a in these mice." (PMID 33364514, 2020). "The question remains whether it is the presence of hyperglycemia that stimulates the production of FGF21 in PPGL." (PMID 30959789, 2019). "Thus, the prevention of hyperglycaemia through protein restriction is compromised by high dietary carbohydrates despite increased FGF21 levels." (PMID 29550873, 2018). "An important finding is that protein restriction did not prevent hyperglycaemia and beta cell loss under conditions of a high-carbohydrate diet (LP/HC) despite increased FGF21 levels." (PMID 29550873, 2018). "Thus, we were able to demonstrate that administration of LY2405319 produced substantial effects in vivo to ameliorate hyperglycemia and to reduce excess adiposity, similar to FGF21." (PMID 23536797, 2013). "Indeed, administration of recombinant wild type FGF21 to diabetic rodents leads to a rapid and robust lowering of hyperglycemia, improvements in circulating/tissue lipid levels and reduced body weight." (PMID 23823755, 2013). "Therefore, it is proposed that in the fasted state FGF-21 leads to hyperglycemia by stimulating lipolysis, ketogenesis, gluconeogenesis and increasing insulin sensitivity, while in the fed state, FGF-21 induces hypoglycemic effects by stimulating lipogenesis and adipocyte differentiation." (PMID 36362225, 2022). "Nevertheless, as FGF21 also exerts antioxidative actions, its up-regulation in cases of fetal hyperglycemia and macrosomia may offer protection against oxidative stress, which is the main pathway leading to short-term tissue dysfunction and long-term tissue damage." (PMID 34564397, 2021). "Thus, the effects of IOE to ameliorate hyperglycemia and adiposity may be mediated through FGF21 activating insulin signaling and increasing the expression of GLUT4 and pro-thermogenic factors." (PMID 31323977, 2019). "Although initial clinical data provide encouraging signs of efficacy in humans, it is unclear if FGF21 could provide clinically meaningful improvements in hyperglycemia or more robust and durable responses in other metabolic parameters under chronic treatment conditions." (PMID 26594197, 2015). "Acute FGF21 treatment suppressed hepatic glucose production, increased liver glycogen, lowered glucagon and improved glucose clearance in ob/+ mice, while chronic FGF21 treatment ameliorated fasting hyperglycaemia in ob/ob mice via increased glucose disposal and improved hepatic insulin sensitivity." (PMID 25823710, 2015). "In summary, our results establish hepatic PTP4A1-mediated activation of the CREBH/FGF21 axis as a novel therapeutic strategy in NAFLD and hyperglycemia." (PMID 36793871, 2023). "Lacking PTP4A1 in mice fed an HF diet exhibited hepatosteatosis and hyperglycemia, which were recovered by liver-specific PTP4A1 or systemic FGF21 overexpression." (PMID 36793871, 2023). "While HFCD induced hyperglycemia as compared to LFCD, FGF21 normalized fasting plasma glucose compared to LFCD, which was accompanied by lower glucose excursion after an intraperitoneal glucose tolerance test (IPGTT)." (PMID 36648330, 2023). "BMI correlated inversely with changes of PD-L1 and CD40 during hyperinsulinemia, Oncostatin-M, TNFSF14, FGF-21 and 4EBP-1 during hypoglycemia and CCL23, VEGF-A and CDCP1 during hyperglycemia (Rho ≤ -0.50)." (PMID 37400734, 2023). "Nuclear Erythroid Factor-Related Factor 2 (Nrf2) and Fibroblast Growth Factor 21 (FGF21) are two antioxidant factors that are increased by oxidative stress and hyperglycemia." (PMID 36109786, 2022).
Hyperglycemia (continued). "Both transgenic overexpression and exogenous administration of supraphysiologic levels of FGF21 in genetic- or diet-induced obese (DIO) rodents, substantially reduces body weight, hypertriglyceridaemia and hyperglycaemia." (PMID 36064109, 2022). "Both FGF21 and AMPK augment glucose uptake and reduce hyperglycemia as well as enhance free fatty acid oxidation and energy expenditure." (PMID 29444136, 2018). "The mechanism by which FGF21 and FGF19 ameliorate hyperglycemia in diabetic animals is not well understood." (PMID 21437243, 2011). "Using FGF21 supplementation and knockout of FGF21, we evaluated if FGF21 promoted physiological retinal vessel growth through activation of the APN pathway in a mouse model of hyperglycemia-induced vascular growth suppression (a model of the contribution of metabolism to Phase I retinopathy)." (PMID 36943533, 2023). "Therefore, we used a known activator of APN, fibroblast growth factor 21 (FGF21), which is a key regulator of APN production and secretion in diabetic patients and mice with hyperglycemia." (PMID 36943533, 2023). "We did not observe significant changes in blood glucose levels in hyperglycemic mice, suggesting that FGF21 mainly targeted lipid pathways rather than lowering hyperglycemia." (PMID 36943533, 2023). "Pharmacologic inhibition of 5-HT2BRs ameliorates hyperglycemia associated with alterations of hepatic FGF21 and 5-HT2AR expression and plasma FGF21 levels without affecting food intake and body weight in obese and diabetic mice such as KKAy and db/db mice." (PMID 35163521, 2022). "In line with this, elevated serum levels of FGF21 are reported in patients suffering from severe clinical syndromes with a negative correlation on mortality independently of hyperglycaemia." (PMID 36415151, 2022). "In summary, without changes in total fat mass, FGF21 prevents hyperglycaemia and improves glucose clearance in NZO mice fed a carbohydrate-containing diet." (PMID 28770320, 2017). "Increased plasma levels of glucagon‐like peptide 1 (GLP‐1) and FGF‐21 were found to contribute to the improved glycemic control in Gcgr−/− mice and to work in a complementary way to prevent postprandial hyperglycemia in mice lacking insulin and glucagon action." (PMID 39985139, 2025). "Taken together, these data suggest that hyperglycemia may not play a major role in the modulation of FGF21." (PMID 26540514, 2015). "To date, it has not been determined whether FGF21 based therapy, often deemed to correct hyperglycemia via an insulin sensitization mechanism, remains efficacious with regard to glucose endpoints in the context of low insulin levels." (PMID 23823755, 2013). "Therefore, it was not known whether some individuals already had hyperglycemia at 14 to 21 weeks of gestation, which brought a certain degree of uncertainty in the clinical value of the availability of high FGF21 levels." (PMID 33995273, 2021). "Furthermore, an in vitro study showed that FGF21 supplement protected the cardiomyocytes against lipotoxicity rather than glucose toxicity, indicating that FGF21-induced cardiac protection in T2DM mice is mainly attributed to the prevention of lipotoxicity rather than hyperglycemia." (PMID 29445083, 2018). "In addition, the VLCD-induced reduction in fasting hyperglycemia was observed without any changes in hepatic ceramide content, hepatic inflammatory cytokine concentrations, or plasma concentrations of glucagon, corticosterone, or fibroblast growth factor-21 (FGF-21)." (PMID 41009753, 2025).
steatosis (107 papers, 2011 to 2026). Increased lipid within the cytoplasm of cells. "Deficiency of FGF21 favors the development of steatosis, inflammation, hepatocyte injury and fibrosis in the liver, while administration of FGF21 analogues improves NASH by attenuating these processes." (PMID 37361533, 2023). "The detection of a high FGF21 serum level in these patients was associated with MetS, lipodistrophy, and severe steatosis." (PMID 35355551, 2022). "Feeding a high fat, high sucrose (HFHS) diet, fibroblast growth factor 21 (FGF21) deficient mice developed advanced steatosis and liver fibrosis, with liver inflammation compared to wild-type mice." (PMID 35002979, 2021). "Results of meta-analysis showed that FGF-21 serum level was remarkably higher in non-alcoholic fatty liver disease than simple steatosis as well as having a diagnostic score, odds ratio, and specificity of 1.74, 5.7, and 0.78, respectively." (PMID 33810243, 2021). "Obesity, elevated body mass index (BMI), and steatosis are positively linked with FGF21 levels." (PMID 40430469, 2025). "Additionally steatosis, inflammation, hepatocyte damage, and fibrosis in the liver can develop from FGF21 deficiency, whereas FGF21 analogue administration or upregulation of its endogenous level attenuates these processes." (PMID 36296980, 2022). "FGF21 deficiency has been proved to promote the development of inflammation, intrahepatic steatosis, hepatocyte damage, and fibrosis, whereas FGF21 analogs have potentially been introduced to inhibit nonalcoholic steatohepatitis (NASH) by weakening these processes." (PMID 35408949, 2022). "Potential interventional drugs or measures have been reported in multiple preclinical studies and the medications susceptible to be active in steatosis such as fibroblast growth factor 21 agonists, obeticholic acid or glucagon-like peptide-1 agonists deserve considerations." (PMID 34707997, 2021). "Interestingly, an improvement in steatosis was observed in response to FGF21 although the deficiency to hepatic lipids in these models often limits treatment effects on steatosis." (PMID 33414764, 2020). "The FGF21 deficient mice were found to have worsened steatosis, inflammation, and fibrosis." (PMID 27699175, 2016). "This stress-activated FGF21 expression may underlie the generally beneficial effects of FGF21 through alleviating liver overload such as steatosis and counteracting potential liver damage imposed by a variety of metabolic and cellular stresses." (PMID 23590285, 2013). "In contrast, other authors have reported similar FGF-21 levels in groups with different severity levels of steatosis, inflammation, and fibrosis." (PMID 40430125, 2025). "Liver-specific Zfp36l1KO mice showed protection against the development of steatosis after a Lieber–DeCarli liquid diet, as well as an increase in FGF21 mRNA, a protective factor of steatosis, which is directly inhibited by BRF1." (PMID 39941720, 2025). "The improvement of fibrosis and steatosis in patients with NASH coincides with a reduction in FGF21 levels." (PMID 40430469, 2025). "FGF21 was loosely related to steatosis grades, and although for lobular inflammation scores 1 and 2 FGF21 expression increased (box‐plots), we computed and inverse relationship." (PMID 39962359, 2025). "In regards to steatosis, the frequency of score 1 was about 1.8‐fold higher in patients with unchanged FGF21 expression." (PMID 39962359, 2025). "Independent studies reported FGF21 to improve hepatic inflammation and steatosis, and in our study, we found patients with increased FGF21 expression to be less frequently scored 3 for lobular inflammation." (PMID 39962359, 2025). "MR also induces metabolic reprogramming in liver and brain, enhancing fatty-acid oxidation and Fibroblast growth factor-21 (FGF21) secretion, potentially delaying steatosis and neurodegeneration." (PMID 41470779, 2025).
steatosis (continued). "In contrast, hepatocytes from the FGF21-164-treated group displayed a smaller cross-sectional area compared to the model, indicative of attenuated steatosis and restored cellular architecture." (PMID 40141314, 2025). "There is evidence that serum FGF-21 is a useful marker for steatosis and correlates with increasing steatosis grade." (PMID 38886851, 2024). "In liver, FGF21 knockout lead to visible change like fatty liver such as hepatocyte ballooning steatosis and mixed inflammatory infiltration." (PMID 38653921, 2024). "The administration of FGF21 to obese mice improves hepatic autophagy and steatosis via the Jumonji-D3 signaling pathway." (PMID 37998747, 2023). "Whereas knocking down Fgf21 using adenoviral expression of short hairpin RNA targeting FGF21 in high-fat diet fed transgenic mice resulted in the mitigation of steatosis but exacerbation of hepatic injury and inflammation." (PMID 37284280, 2023). "Some researchers fed FGF21 knockout mice with a ketogenic diet and found that fat levels in the plasma of the mice were increased, obvious steatosis occurred, and the regulatory function of ketogenesis and sugar metabolism was impaired." (PMID 37233635, 2023). "Pemafibrate treatment increased serum FGF-21 levels, leading to improved liver function and the alleviation of inflammation and steatosis of the liver." (PMID 37880780, 2023). "They performed a high-throughput quantitative polymerase chain reaction and found that FGF21 administration affects more hepatic genes than caloric restriction to improve steatosis and inflammation." (PMID 36594101, 2023). "Phase 3 clinical trials verified that serum FGF21 was elevated in pemafibrate-treated groups, possibly leading to improved liver function as well as improvements in inflammation and steatosis of the liver." (PMID 37514025, 2023). "MSI-S, as a novel non-invasive index, based on mitochondrial stress biomarker FGF21 effectively predicted steatosis." (PMID 35663311, 2022). "In the treatment of non-alcoholic steatohepatitis, FGF21 and its analogs have shown encouraging outcomes, and FGF21 can prevent the deterioration of steatosis, inflammation, hepatocyte injury, fibrosis, and cirrhosis in observed non-alcoholic steatohepatitis." (PMID 36703750, 2022). "An elevation in FGF21 levels was detected in patients with metabolic steatohepatitis compared to those with simple steatosis (p < 0.001)." (PMID 34141520, 2021). "Collectively, we have demonstrated that Camp–/– mice are protected against HFD plus alcohol-induced liver injury and steatosis through FGF21/adiponectin regulation." (PMID 34943840, 2021). "Taken together, the bioactivities of FGF15 on hepatocytes, instead of alleviating lipid accumulation, was shown to up-regulate FGFR4, while compromised FGF21 worsened steatosis in hepatocytes." (PMID 34326695, 2021). "FGF19 and FGF21 analogues have overlapping effect on steatosis, inflammation and fibrosis in mice and human subjects." (PMID 33414764, 2020). "Rodent studies have also demonstrated a positive relationship between FGF21 and adiponectin, while also shown that the beneficial effects of FGF21 on steatosis are ablated in adiponectin knock-out mice." (PMID 33071964, 2020). "FGF21 [0.661 (0.589–0.773); P < 0.001] can predict the onset of simple steatosis while M30 [0.427 (0.353–0.502); P = 0.077] cannot, and M65ED showed an area under curve (AUC) of 0.581 (0.502–0.660); P = 0.049." (PMID 28698650, 2017). "Histopathological scoring confirmed severe macrovesicular steatosis and fibrosis in FGF21-KO-LDC mice." (PMID 29107287, 2017). "Several studies have observed that KD feeding increase inflammation and fibroblast growth factor 21-mediated hepatocyte steatosis in rodents." (PMID 28914762, 2017). "Our results demonstrated that FGF21 is more accurate for predicting the onset of simple steatosis, while CK18 including M30 and M65ED are better biomarkers for monitoring the prognosis of NAFLD patients." (PMID 28698650, 2017).
steatosis (continued). "Despite the protective nature of FGF21 in animal models, many clinical studies have reported a positive correlation between steatosis and fibrosis severity and serum FGF21 levels in humans." (PMID 27699175, 2016). "We find that hepatic FGF21 expression correlates well with the degree of steatosis in various rodent models, and CREBH plays a critical role in FGF21 expression." (PMID 27301791, 2016). "A recent study showed that the Tsc1-/- livers are protected from steatosis through ‘stress’-induced responses, including hepatic synthesis of FGF21, but we were unable to find significant differences in FGF21 expression in livers of various genotypes." (PMID 25646773, 2015). "Forced FGF21 expression in partial hepatectomized hPPARαPAC reduced hepatic steatosis, prevented focal necrosis, and restored liver mass." (PMID 25991671, 2015). "Continuous subcutaneous infusion of recombinant FGF21 for 4 weeks in Fgf21 KO animals reverse steatosis and peroxidative damage, suggesting a direct and perhaps adipose independent role of FGF21 in liver fatty acid activation and oxidation." (PMID 26594197, 2015). "In Fgf21 transgenic mice, Fgf21 acts as an inducer for hepatic ketogenesis and steatosis and for adipocyte lipolysis." (PMID 23874946, 2013). "FGF21 expression was lost or attenuated in cells with abnormal and irregular expansion of nuclei (yellow arrows) accompanied by focal steatosis (black asterisks) and cirrhosis (blue arrows) in surrounding hepatocytes (8 and 12 months)." (PMID 23590285, 2013). "Yan and colleagues reported lower FGF21 levels in severe steatosis as evaluated by magnetic resonance imaging." (PMID 23840612, 2013). "FGF21 comes into play after prolonged periods of caloric restriction or hepatic perturbation by conditions such as steatosis or chemical damage." (PMID 23106963, 2012). "In addition, it has been reported that the hepatoprotective role of FGF21 in females depends on intact estrogen signaling, as ovariectomy abolished FGF21-mediated resistance to diet-induced steatosis unless estrogen was restored." (PMID 41516073, 2025). "Interestingly, these elevated circulating levels of FGF21 have been highlighted in NAFLD patients by a meta-analysis where the levels of FGF21 showed one of the best sensitivities to segregate NASH from steatosis patients." (PMID 38519536, 2024). "In the setting of moderate to advanced fibrosis, FGF-21 may lose its power as a predictive marker of steatosis as it would mostly be affected by ECM deposition." (PMID 37999215, 2023). "In our study, we also found that SCF, TWEAK, and IL-18R were also associated with steatosis before treatment, while FGF-21 was not." (PMID 37371624, 2023). "Moreover, FGF21 abolished the HFCD-induced increase in steatosis, lobular inflammation, and hepatocellular ballooning." (PMID 36648330, 2023). "Interestingly, hepatic expression of FGF21 fully prevented the diet-induced increase in liver weight, liver lipids (i.e., TG and TC), and steatosis score." (PMID 36648330, 2023). "Moreover, they also showed inhibition of miR-22 eliminates alcohol-induced steatosis in murine models, possibly due to restoring FGF21 expression." (PMID 35498403, 2022). "FGF21 was one of the strongest independent predictors for the severity of steatosis." (PMID 35663311, 2022). "However, in a previous study, we showed an important part of these mechanisms in which we observed that FGF21 increased in response to CS treatment thereby reducing steatosis, inflammation, and fibrosis in the NASH animal model." (PMID 36192786, 2022). "In terms of the specific effects of FGF21 on the liver, many studies have indicated that FGF21 could protect against the development of steatosis and nonalcoholic fatty liver disease." (PMID 34997461, 2022). "Accordingly, FGF21 might be sensitive in diagnosing mild or moderate steatosis and predicting the onset of simple steatosis." (PMID 36457562, 2022).